CD4 (CD4 molecule)
Diseases named in the same sentence as CD4 in open-access papers (continued):
Sharing a sentence is not in itself a finding about the gene and the disease.
lung cancer (continued). "They showed a higher percentage of CD8+ cells with (s)CTLA-4 and a higher percentage of CD4+ cells with (in)CTLA-4 in the lung cancer patients as compared to the healthy subjects." (PMID 27866241, 2017). "For the CD4+ cell levels in lung cancer, there were 14 clinical trials including 518 patients in the SQI intervention and 499 patients with conventional chemotherapy." (PMID 28154607, 2017). "DC-based HHP lung cancer vaccine decreased the number of CD4+CD25+Foxp3+ T regulatory cells and stimulated IFN-γ-producing tumor antigen-specific CD4+ and CD8+ T cells from non-small cell lung cancer (NSCLC) patients." (PMID 28187172, 2017). "We measured the proportion of CD4+CD25+FOXP3+ Treg and the expression level of FOXP3 mRNA in peripheral blood to explore the underlying interaction among age, Treg and lung cancer susceptibility." (PMID 28253320, 2017). "The findings that a) CD4+ lymphocytes are decreased and b) Annexin V staining is increased are consistent with a more profound immunosuppressive state in mice with lung cancer followed by CLP compared to previously healthy mice subjected to the same insult." (PMID 27018973, 2016). "Studies have shown that the composition of Tregs and Th17 cells are altered in the tumor microenvironment, and that these two CD4+ T cell subsets play active roles in promoting lung cancer progression and metastasis." (PMID 27784305, 2016). "There is compelling evidence that this is due to the immunosuppressive effects of CD4+ T cells, which play a central role in orchestrating the immune response to lung cancer." (PMID 26871598, 2016). "We previously reported, in malignant pleural effusion from lung cancer patients, similar percentages of CD4+ROR-γt+ T-cells and IL-17-producing Th17 cells." (PMID 26582240, 2015). "Some groups have reported that Th17 cells (detected as IL-17-producing CD4+ T-cells) are increased in peripheral blood of lung cancer patients; our data agree with these previous reports." (PMID 26582240, 2015). "Even more important, the presence of CD4+ T-lymphocytes in the bronchioalveolar lavage fluid (BALF) of irradiated breast or lung cancer patients correlated with a pneumonitic reaction." (PMID 24766907, 2014). "It is known from preclinical and clinical investigations that CD4+ and CD8+ T-lymphocytes constitute a significant part of the immune cell infiltrate in the lung tissue of irradiated breast and lung cancer patients with a predominance of the CD4+ subset." (PMID 24766907, 2014). "A significant negative correlation between IFNG plasma levels and total IFNG promoter methylation in CD4+ T cells of lung cancer patients was observed." (PMID 24244422, 2013). "In our study, we observed decreased levels of plasma IFNG and intracellular IFNG in CD4+ T cells from lung cancer patients." (PMID 24244422, 2013). "A transwell culturing system was used to investigate the effect of the lung cancer cell line SPC-A1 on IFNG expression of CD4+ T cells." (PMID 24244422, 2013). "A lower frequency of IFNG producing CD4+ T cells were detected in lung cancer patients compared with healthy controls (P<0.001)." (PMID 24244422, 2013). "The interaction between lung cancer cells and CD4+ T cells induces hypermethylation of the IFNG promoter in CD4+ T cells, which serve as a mechanism of tumor-induced immunosuppression." (PMID 24244422, 2013). "Methylation at CpG sites of the IFNG promoter in CD4+ T cells of lung cancer patients and healthy controls." (PMID 24244422, 2013). "Subgroup analysis indicated that acupoint insertion and injection with herb extraction are able to elevate the total T cells (CD3+) and T helper cells (CD4+) in lung cancer patients." (PMID 24344728, 2013). "The result of IFNG promoter methylation of CpG sites demonstrated hypermethylation was similar to that observed in CD4+ T cells of lung cancer patients (85.4% vs 85.4%), which generated lower levels of IFNG upon activation." (PMID 24244422, 2013).
lung cancer (continued). "CAPE was recently reported to suppress phosphorylation of Akt in other human cells, such as CD4+ T cells, coronary smooth muscle cell, and A549 lung cancer cells." (PMID 22347457, 2012). "The percentage of CD3+, CD3+CD4+, CD4+CD25+ cells of the lung cancer patients significantly varied from those of the healthy donors, the P values are 0.012, 0.034 and 0.006 separately." (PMID 22429580, 2012). "We recently found that peripheral blood CD4+ and CD8+ T-cells from lung cancer patients show a high susceptibility to spontaneous apoptosis compared with T-cell subpopulations from healthy donors." (PMID 23118782, 2012). "On immunohistochemical analysis, we observed high numbers of CD8+ T cells and CD4+ T cells near one another in the tumors formed by Caski and HeLa cervical cancer cells, as well as A549 lung cancer." (PMID 21649881, 2011). "In lung cancer the prognostic impact of CD4 is controversial, but in our material CD4+ cells were a positive prognostic factor in univariate analyses." (PMID 21298041, 2011). "In lung cancer patients cortisol, TRH, TSH and GH serum level and all the lymphocyte subsubsets variation (except for CD4) showed loss of circadian rhythmicity." (PMID 20565977, 2010). "Reduction of CD4+ T lymphocytes by administration of anti-CD4 antibody allowed human lung cancer xenografts to form orthotopically in immuno-competent mice." (PMID 16421594, 2006). "Similarly, DC-based high hydrostatic pressure (HHP) lung cancer vaccine decreased the number of CD4+CD25+Foxp3+ Tregs and Increased IFN-γ-producing tumor antigen-specific CD4+ and CD8+ T cells from non-small cell lung cancer (NSCLC) patients." (PMID 40050933, 2025). "Even after adjusting for smoking status, a 1.7‐ to 2.4‐fold increased risk for lung cancer among people living with HIV remains, suggesting additional contributions from HIV‐related immune impairment caused by persistent CD4+ T cell deficiency, chronic inflammation and other comorbid factors." (PMID 41190419, 2025). "However, in the setting of lung cancer, activin promotes CD4 to CD8 T-cell communication to enhance cytotoxicity and tumor cell elimination." (PMID 40075112, 2025). "Therefore, we purified SP-MDSCs and T-MDSCs in a mouse lung cancer xenograft model and co-cultured them with CD4+ T cells (1:1) derived from the spleen of wild-type mice." (PMID 40917754, 2025). "The current meta-analysis suggests that the administration of general anesthesia in conjunction with epidural anesthesia is associated with elevated CD3+ and CD4+ T cell counts, as well as an increased CD4+/CD8+ ratio in patients undergoing lung cancer surgery." (PMID 40731892, 2025). "Notably, we demonstrate that differential core and marginal CD4+ cell quantifications of whole tumor tissues derived from patients with non–small cell lung cancer (NSCLC) after neoadjuvant αPD-L1 therapy were predictive of therapy resistance." (PMID 40561008, 2025). "Moreover, in comparison to COPD, lung cancer demonstrated higher infiltration of CD4 + T cells and lower infiltration of CD8 + T cells." (PMID 38605291, 2024). "The immune response in lung cancer relies heavily on tumor-infiltrating CD4+ T cells." (PMID 38509982, 2024). "In addition, the T cells predominated in lung cancer immune landscape, and CD4+ T cells and CD8+ T cells were the common prevalent T cell subtypes." (PMID 38382091, 2024). "However, the role of CD4+ Th cells in HIV-related lung cancer is still controversial, suggesting that more research is needed on this topic." (PMID 38542056, 2024). "Within the subtypes of CD4 + T cells, we found a significant increase in Treg cell infiltration in both COPD and lung cancer, with Treg cells acting as intermediate factors mediating the causal association between COPD and lung cancer." (PMID 38605291, 2024).
lung cancer (continued). "While it is wellknown that HIV lowers CD4 T-cell counts, which potentially affects immune surveillance and cytotoxicity against cancer cells, the association between low CD4 counts and lung cancer is not consistently observed." (PMID 38292339, 2024). "Box plots of differences in immune cell infiltration showed that compared with the control group, memory B cells, activated myeloid dendritic cells, M0 and M1 macrophages, plasma cells, CD4 + memory activated T cells were significantly increased in the lung cancer group." (PMID 38468345, 2024). "Besides, the homeostasis formed by each subset of CD4 + T cells is of weight for maintaining the immune function of lung cancer patients." (PMID 38172945, 2024). "The lower median CD4 count in lung cancer patients is another observation in our study which could be attributed to the lower ART coverage among the cases compared to the controls." (PMID 38292339, 2024). "For example, the CD8, CD20, CD68, and CD4-positive exclusion group had the lowest degree of ITGAL-expressing cell infiltration in lung cancer tissues, whereas the inflamed group had the highest degree of ITGAL-expressing cell infiltration in lung cancer tissues." (PMID 38646528, 2024). "Neoantigens are generated during tobacco smoking both in COPD and lung cancer, and naive CD4+ T cells are exposed to HLA-demonstrated epitopes that may lead to the development of antigen-specific long-lived memory T cells." (PMID 38187374, 2023). "Previous flow cytometry studies on mesothelioma and lung cancer patients suggest that CD4+ regulatory T cells are recruited to the pleura and report high proportions of CD4+ T cells relative to CD8+ cells in MPEs,36, 37, 38 where CD8+ T cell dominance has been observed in non‐MPEs." (PMID 37691350, 2023). "The CD4+ memory T cells were constitutively presented in the microenvironment of lung cancer, which could be mobilized by IL-12 to proliferate and kill tumor cells in the xenograft." (PMID 36793597, 2023). "In addition, the CXCL13+CD4+ T cell subset indicated in lung cancer has been described by high expression of exhaustion markers, including PDCD1, CTLA4, TIGIT, and HAVCR2, which is considered as an exhausted CD4+ T cell subpopulation." (PMID 37187731, 2023). "Several studies have shown that the composition of Tregs and Th17 cells may be altered in the tumor microenvironment, and that these two CD4 + T cell subsets play active roles in promoting lung cancer progression and metastasis." (PMID 36814205, 2023). "Moreover, accumulation of CD4+FOXP3+ Tregs was reported to correlate with increasing incidence of lung cancer." (PMID 35688943, 2022). "Additionally, another study demonstrated that TIM-3 is highly expressed on both CD8+ and CD4+ T cells in TILs, but insignificantly in PBMCs in human lung cancer tissues." (PMID 36146549, 2022). "Meanwhile, we found that compared to WT mice, the amount of pulmonary CD4+T cells in Kras-mutated mice was not influenced during of lung cancer progression." (PMID 36033391, 2022). "A previous study revealed that interleukin 12 (IL-12) could promote the proliferation and tumor suppression of memory CD4+ T cells presenting in the tumor microenvironment (TME) of lung cancer." (PMID 35938013, 2022). "In summary, increased DFNA5 expression correlates with a poor prognosis in liver cancers and increased immune infiltration levels of CD8 + T cells, CD4 + T cells, macrophages, neutrophils and DCs of multiple cancers, especially in colon, liver and lung cancers." (PMID 35248047, 2022). "Differences in macrophage types and in CD4/CD8 ratios were observed in lung cancer models." (PMID 35158887, 2022). "CD4+ Th1 cells activated CD8+ T cells, and γδ-T cells are typically implicated in type I immune responses and are associated with a favorable prognosis in patients with lung cancer." (PMID 36263125, 2022).
lung cancer (continued). "Whereas, in contrast to CSCC, the higher expression of COL1A1 could promote lung cancer and mesothelioma progression via immune infiltration mechanisms (including CD4+ T cells, macrophage, neutrophil, and dendritic cell)." (PMID 36085041, 2022). "Therefore, our findings take us a step closer to validating the association between TILs (CD4/CD8) and early-stage tumorigenesis in lung cancer." (PMID 35628157, 2022). "In addition, there is mounting evidence proving the importance of participation of CD8+ or CD4+ T cells and natural killer cells in lung cancer progression 15-18." (PMID 35371315, 2022). "Additionally, co-culture of T cells with ORFV NA1/11-infected lung cancer cells decreased the number of migrated CD4+CD8+ T cells." (PMID 35959371, 2022). "Using the IHC characterization of TILs, we found that CD4 lymphocytes were high and very high within the stromal compartment in 84.4% of the early-stage lung cancer cohort, while the CD8 cells were lower in abundance, showing a moderate and low abundance in 64.7% of the cases." (PMID 35628157, 2022). "Moreover, there was a significant correlation between TMPRSS2 expression and the infiltration abundances of CD8+ T cells, CD4+ T cells, B cells, neutrophils, macrophages, and dendritic cells in lung cancer." (PMID 35017320, 2022). "We report for the first-time αTIGIT in combination with bintrafusp alfa results in prominent antitumor activity and increase in overall survival in both the MC38-CEA colon carcinoma and the TC1, HPV+ lung carcinoma models, which are dependent on CD4+ and CD8+ T cells." (PMID 36211806, 2022). "In summary, the low expression of CFP is closely related to the prognosis of multiple tumors (especially lung cancer and gastric cancer), and is associated with increased infiltration of immune cells such as CD8+ T cells, CD4+ T cells, macrophages and neutrophils." (PMID 33976747, 2021). "For instance, in lung cancer, the “mesenchymal” phenotype is associated with distinct TME changes, including the elevation of immune checkpoint molecules and the enhanced tumor infiltration by CD4+Foxp3+ regulatory T cells and CD3+ T cells." (PMID 34277389, 2021). "In lung cancer, tumor-infiltrating CD4+ T cells play an essential role in the immune response." (PMID 34168239, 2021). "A research in mice that received subcutaneous implantation of lung cancer cells showed that the expression of BTLA on CD4+ T cells and CD8+ T cells increased and the number of these T cells increased as well, while BTLA+/CD8+ T cells produced less IL-2 and TNF." (PMID 34163466, 2021). "The results of the meta-analysis showed that the combination treatment (Shenmai injection plus chemotherapy) could significantly increase the proportion of CD3+ and CD4+ in the T-lymphocytes of patients with lung cancer." (PMID 33936245, 2021). "However, T cell cloning of responding cells from one patient (results not shown) and intracellular cytokine staining assessed by flow cytometry in the lung cancer UV1 vaccine study confirmed that the majority of responding T cells were CD4+." (PMID 34046035, 2021). "The survival curve of this study showed that peripheral CD4+ T cells but not CD8+ T cells were associated with OS in lung cancer." (PMID 33859531, 2021). "Tumor-infiltrating B cells could efficiently present antigen to tumor-infiltrating CD4 T cells and alter the CD4 cells’ phenotype using an antigen-presentation assay, which further served as a potential therapeutic target in lung cancer immunotherapy." (PMID 34177903, 2021). "However, some scholars hold the view that CD4+TN level in smoking lung cancer is correlated with favorable prognosis." (PMID 34777388, 2021). "Thus, the impact of this study lies on the envision of utilizing activin-A-conditioned CD4+ T cells in future therapeutic modalities of lung cancer." (PMID 34548096, 2021).
lung cancer (continued). "We suppose that high CD28 expression may be due to CD4+ T-cell activation related to micrometastases in LNs in lung cancer patients and may control the metastatic cells in these compartments." (PMID 32808188, 2021). "Given that activin-A exhibits a profound effect on CD4+ T cells in the airways and is elevated in lung cancer patients, we hypothesized that activin-A can effectively regulate anti-tumor immunity in lung cancer." (PMID 34548096, 2021). "In addition, we only observed high CD4+ T‐cell counts in patients with lung cancer compared to controls." (PMID 32459060, 2020). "Moreover, P-selectin expression was higher in lung cancer patient CD4+ and CD8+ PTCAs compared to those from healthy volunteers." (PMID 32776968, 2020). "We found lower levels of lymphocyte and CD4+ T lymphocyte linked with radiation pneumonitis and dynamic change of lymphocyte and CD4+ T lymphocyte predict radiation pneumonitis after 182 cases of lung cancer patients with radiation pneumonitis were retrospectively analyzed." (PMID 32207253, 2020). "A reduction in the CD4+/CD8+ ratio is common in lung cancer patients after chemotherapy cycles, indicating an inhibition of the immune function in which the immune system's ability to recognise and kill mutant cells is weakening, leading to tumour growth and metastasis." (PMID 33110435, 2020). "The interaction between CD4+ T cells and lung cancer cells could up-regulate expression of DNMT and methylation of IFNG promoter." (PMID 32296631, 2020). "Lung cancer patients had more activated platelets in both CD4+ and CD8+ PTCAs." (PMID 32776968, 2020). "Regarding T cells, it is currently believed that high CD4+ T lymphocyte infiltration in tumor stroma, rather than in tumor cell nests, is correlated with better OS in lung cancer patients 44, while regulatory T cells are associated with a poorer prognosis." (PMID 32624696, 2020). "Interestingly, lung cancer‐specific CD4 T cells were present at varying proportions before the start of immunotherapy in both G1 and G2 patients." (PMID 31273938, 2019). "Furthermore, we found that expanded DNT cells exerted a greater cytotoxicity against lung cancer in vitro compared to CD4 and CD8 T cells from the same donor." (PMID 30857561, 2019). "Similarly, we found a statistically significant increase in CD4+CD25+FoxP3+ frequency in MPEs over the course of lung cancer, with the highest Treg percentage in MPEs with malignant cells." (PMID 29785404, 2018). "Moreover, CD4+ T cells from healthy donors cocultured with SPC‐A1 cells (lung cancer cell line) resulted in a reduction in IFNγ expression after stimulation, an increase in DNA methyltransferases (DNMTs) and hypermethylation of the IFNγ promoter." (PMID 30039553, 2018). "Importantly, the numbers of CD4+ T cells are positively correlated with a favorable prognosis in lung cancer patients." (PMID 28101811, 2017). "However, IFN-γ-producing CD8+ and CD4+ T cells were also significantly stimulated by DC treated only with poly(I:C) similarly to DC-based HHP lung cancer vaccine." (PMID 28187172, 2017). "Similarly, higher proliferation of CD8+ and CD4+ T cells was detected after DC-based HHP lung cancer vaccine stimulation." (PMID 28187172, 2017). "The high frequency of CD4+ T cells in TILs and malignant pleural effusions (MPEs) correlates with a favorable prognosis in lung cancer patients; however, other studies indicate that the high number of CD8+ T cells, not CD4+ T cells, in TILs has a good clinical outcome." (PMID 28101811, 2017). "Comparison of CD4+CD25+FOXP3+/CD4+ T cells in lung cancer patients." (PMID 28253320, 2017).